HTRA2 (HtrA serine peptidase 2)
Diseases named in the same sentence as HTRA2 in open-access papers (continued):
Sharing a sentence is not in itself a finding about the gene and the disease.
metabolic disorders (3 papers, 2016 to 2022). "To fully understand the effect of HtrA2/Omi on hepatic steatosis and related metabolic disorders, we further set up hepatic HtrA2/Omi-overexpressed mice models through tail-vein injections of AAV8-TBG-mNeongreen-HtrA2/Omi." (PMID 35449197, 2022). "Thus, an HtrA2 deficiency may have no response to RA associated with a metabolic disorder." (PMID 28008946, 2016).
neurological disease (2 papers, 2018 to 2021). "In accordance, overactivation of the HTRA2 proteolytic function has already been reported in AD as well as other neurological diseases, and is known to trigger autophagy." (PMID 34440217, 2021).
peripheral neuropathy (2 papers, 2015 to 2018). A disorder affecting the peripheral nervous system. "The most prominent clinical adverse event included peripheral neuropathy, caused by off-target inhibition by BTZ of a neuronal survival protein, HtrA2/Omi." (PMID 29184971, 2018). "Peripheral neuropathy appeared to be related to non-proteasomal inhibition by BTZ of HtrA2/Omi, a neuronal survival protease." (PMID 25889583, 2015).
cardiovascular diseases (1 paper, 2019). "Studies have shown that mitochondrial dysfunctions associated with HtrA2/Omi is a key causative factor inducing cell death in various chronic pathological conditions in numerous human diseases, such as neurodegeneration and cardiovascular diseases." (PMID 31547195, 2019).
HTRA2 also shares sentences with these, for which no sentence is quoted: brain ischemia (2 papers); cognitive disorder (2); frontotemporal dementia (2); genetic disorder (2); osteoarthritis (2); viral infection (2); age-related macular degeneration (1); bladder cancer (1); cardiac hypertrophy (1); cataract (1); colon carcinoma (1); Dyskinesia (1); familial hypercholesterolemia (1); hereditary ataxia (1); inflammatory bowel disease (1); ischemia reperfusion injury (1); liver cancer (1); lymphopenia (1); lymphoproliferative disorder (1); male infertility (1); malignant thyroid tumors (1); migraine with aura (1); Mitochondrial Dysfunction (1); multiple myeloma (1); myeloid leukaemia (1); neonatal encephalopathy (1); neurodevelopmental disorder (1); non-small cell lung carcinoma (1); osteoporosis (1); osteosarcoma (1).
A further 7 diseases each share a sentence with HTRA2 in 1 paper.